KRAS (KRas proto-oncogene, GTPase)
Diseases named in the same sentence as KRAS in open-access papers (continued):
Sharing a sentence is not in itself a finding about the gene and the disease.
tumor (continued). "As evidenced by clinical studies, KRAS G12C inhibitors did not determine significant tumor shrinkage in about half of the patients included in clinical trials." (PMID 36012655, 2022). "While the high number of SNVs called were associated with tumor purity calls (Pearson’s correlation = 0.51, P = 0.03), the MAF of KRAS G12C was not correlated with tumor purity (Pearson’s correlation = –0.017) in copy-neutral samples." (PMID 34990404, 2022). "The reason for this is the ability to induce tumor initiation that is directly related to the ability of KRAS to suppress Fzd8-mediated non-canonical Wnt/Ca2+ signaling." (PMID 35409064, 2022). "Here, we show a tumor-promoting stabilization mechanism of KRAS via another oncogenic protein, DX2, and propose the interface of the two oncogenic factors as an alternative and effective route to control KRAS-driven cancers." (PMID 35546148, 2022). "Similarly, confocal fluorescence IHC showed higher SOX9 in tumor compared to matched mucosa, with stronger SOX9 immunostaining in KRAS G12D and G12V tumors." (PMID 34919787, 2022). "In addition, the expression levels of KRAS, XPO1, ERK2 and BCL-2 mRNA were found to be significantly decreased in the residual tumor samples from the combination group." (PMID 35573474, 2022). "IHC assay was utilized for the levels of KRAS, β-TrCP, GSK-3β or ANAPC2 in tumor tissues." (PMID 35305671, 2022). "The KRAS protein is a membrane-bound protein which could bind to GTP to activate intracellular signaling pathways, promote tumor cells proliferation, and angiogenesis." (PMID 35630522, 2022). "Targeting of Myc transcription and CD44v6 with dinaciclib and taselisib, respectively, significantly affected the growth of tumor xenografts generated by subcutaneous injection of aggressive KRAS-mutant/MYC-amplified CR-CSphCs, without affecting mice weight." (PMID 35158939, 2022). "Resistance mechanisms to KRAS-RAF-MEK signaling inhibition include genetic alterations of targeted oncogenes and adaptive activation of alternative regulators or signaling pathways in tumor cell intrinsic and extrinsic manners." (PMID 35966590, 2022). "In these head-to-head comparisons, we observed that in only KRAS mutant cell-derived xenograft models, that is, MIA PaCa-2- and BxPC-3 KRASG12V- derived models, DEX-TP outperformed free TP with higher tumor growth inhibition rates." (PMID 35154474, 2022). "A total of 81% (29 patients) of the BRAFWT cases harboured a KRAS mutation, whereas none of the BRAFMUT tumours did so (p < 0.0001)." (PMID 34877621, 2022). "Although found in one of the in ovo tumors, somatic KRAS alteration is found with greater heterogeneity (absent in the initial tumor sample, but present in liquid biopsies)." (PMID 36077622, 2022). "Oncogenic KRas, which is present in virtually all PDACs, represses miR-143/miR-155 expression and this could contribute to the PDAC tumor microenvironment." (PMID 35883598, 2022). "The concordance of KRAS mutation was higher between PPE and paired neoplasia samples (EAH and carcinoma, 13/18, 72.22%) compared with normal (16/48, 33.33%) and hyperplasia tissues (1/7, 14.29%, P < 0.01)." (PMID 35796805, 2022). "Since RAS signaling is closely related to malignant tumor proliferation, we hypothesized that ZNF24 may promote the progression of KRAS mutant LUAD by upregulating SLC7A5 protein expression." (PMID 36505791, 2022).
tumor (continued). "Among all tested parameters correlated with PFS, gender, age, tumor location, tumor grade, stage, and KRAS as well as BRAF status did not affect PFS or OS by using a Cox regression model." (PMID 35185898, 2022). "Other copy number reduced genes included SMAD4, HNF1B, and some gene loci that are not known to be tumor suppressor genes, such as KRAS, MYC, PIK3CA, and IL6." (PMID 36430324, 2022). "Finally, we directly confirmed that MYC and KRAS oncogenes regulate the interferon and ISG suppression phenotypes in tumor-derived PDAC and OS models using siRNA knockdown of MYC and MEKi treatment." (PMID 35594991, 2022). "We found inhibition of DDR1/BCR signaling with EGFR/ERBB2 to be effective independent of KRAS mutation type and status in COAD and additional primary tumor model of GBM." (PMID 35664781, 2022). "Sotorasib successfully passed all testing phases, from in vitro KRAS c.34G > T (p.G12C) mutant cell lines to preclinical setting: its activity led to the inhibition of ERK phosphorylation and tumor cell growth, while the PI3K signaling was substantially unaffected." (PMID 36077640, 2022). "Therefore, it is critical to understand the metabolic network and landscape in TME in KRAS-driven NSCLC and how they affect the behavior of tumor cells and the function of stromal cells." (PMID 35582540, 2022). "This spike in exosomal DNA KRAS MAF is likely due to the development of treatment resistance and a resultant increase in tumor growth, therefore this early indication would allow for a change of therapeutic regime, preventing unnecessary toxicity and enabling more efficacious treatment." (PMID 35454933, 2022). "Several mechanisms have been described that, at least in cell culture and mouse models of PDAC, allow survival of tumor cells in the absence of mutant KRAS." (PMID 36383067, 2022). "Subgroup analysis of predictive factors for PFS and OS demonstrated that the clinical benefit of this regimen was not related with sex, age, treatment program, primary tumor site, KRAS status, MPV, NLR, LDH and D-Dimer." (PMID 36226061, 2022). "For chromosome 18q11.2‐q12 no‐loss patients with RAS (KRAS and NRAS)/BRAF wildtype tumors and left‐sided location of the primary tumor, anti‐EGFR in the first‐line is a viable alternative, now recommended solely beyond the first‐line." (PMID 35489024, 2022). "The scatterplot of KRAS VAFs between tumor samples prepared by bulk, coring, and LMD showed that cored tumor tissues were most similar to the bulk tumor (R = 0.94), while tumor tissues prepared by LMD showed less similarity to bulk (R = 0.73) or cored tissues (R = 0.75)." (PMID 36266629, 2022). "The tumor and mesenchymal cells in the TME express multiple chemokines and cytokines (e.g., CXCL1, CXCL2, CXCL5, CXCL6, IL1, IL1β, IL6, IL8, IL17, TNFα, and G-CSF), which are regulated by KRAS, SNAIL, and NOTCH signaling." (PMID 35504900, 2022). "Of course, the KRAS mutant NSCLC sample size of the three clinical studies is small, and there are differences in patient characteristics, and all patients in Checkmate 057 study has a PD-L1 tumour proportion score (TPS) of 1% or greater." (PMID 36376839, 2022). "This indicates that ASNS might be a novel therapeutic target for mutant KRAS CRC given its link to increased ASNS expression, Asn generation and propagation of tumor growth." (PMID 36090030, 2022).
tumor (continued). "Notably, the requirement for RAF1 was not limited to tumor initiation, a usually less stringent condition, but extended to tumor progression and maintenance, thus indicating that RAF1 plays a crucial role in KRAS‐driven LUAD." (PMID 34951114, 2022). "NRAS and KRAS are major members of the RAS gene family in mammals, and the proto-oncogene NRAS is abnormally highly expressed in various human malignant tumor tissues and corresponding cell lines, which can promote tumor cell invasion and metastasis." (PMID 35212617, 2022). "The impractical (not tested) KRAS group included patients with metachronous tumours and negative lymph nodes harvested." (PMID 35326950, 2022). "More than 50% of the patients treated with sotorasib and adagrasib do not show significant tumor reduction when treated with these specific KRAS G12C inhibitors." (PMID 35406400, 2022). "Unexpectedly, we found that Notch1 did not impact either oncogenic or tumor-suppressive influence in pancreatic tumorigenesis in the context of mutant KRAS and inactivation of p16." (PMID 36970723, 2022). "Mutation of KRAS bypasses EGFR signalling, nullifying anti‐EGFR‐targeted therapy and so patients with CRC tumours harbouring mutant RAS do not generally receive anti‐EGFR therapy." (PMID 34856074, 2022). "In line with this, several recent studies have demonstrated that autophagy flux is increased upon KRAS or MAPK inhibition in PDAC or other KRAS or RAF-driven cancers, and that the combined inhibition of autophagy and the MAPK pathway exerts potent anti-tumor activity in a synergistic manner." (PMID 36139512, 2022). "Moreover, dual inhibition of IGF1R and KRAS signaling (MEK, mTOR and G12C) markedly enhances anti-tumor effects in CRC and NSCLC cells 132-134." (PMID 35966590, 2022). "Moreover, functional analysis suggested a significant (adjusted p-value < 0.05) enrichment of the MSigDB hallmark gene sets representing major cellular programs known to be frequently hijacked by tumor cells, such as EMT or KRAS signaling." (PMID 35055192, 2022). "KRAS G12C inhibitors solely inhibit the inactive conformation of KRAS G12C, and the subpopulations of isogenic tumor cells respond nonuniformly to the inhibitors." (PMID 36508072, 2022). "Since KRAS inhibition as a monotherapy does not result in prolonged tumor regression in lung cancer, the authors anticipated that combination therapies would likely increase the therapeutic benefit of MRTX1133." (PMID 36383067, 2022). "Also, signatures reflecting oncogenic signalling such as MYC, KRAS, PI3K/mTOR and Notch, were enriched in the tumours of the young." (PMID 35995935, 2022). "Moreover, we detected five different gene amplifications in two different tumor specimens, including MYC (n = 2), PDGFRA, KIT, KRAS, and RICTOR." (PMID 35454843, 2022).
tumor (continued). "The Hippo pathway is a key mechanism driving tumor progression, even in the absence of KRAS activation." (PMID 35804874, 2022). "We started from genes expressed in RAS active conditions, and we identified those that were good markers of KRAS mutants compared with non-activated RAS pathway tumours." (PMID 36163168, 2022). "These isogenic knockdown and pathway inhibition experiments control for genetic complexities between PDAC and OS tumor cells versus normal cells, clearly demonstrating that expression of MYC and KRAS oncogenes drives the ISG suppression phenotype that was identified using unbiased proteomics." (PMID 35594991, 2022). "Studies have shown that in the receptor tyrosine kinase (RTK)-RAS pathway, irrespective of tumor types, Kirsten rat sarcoma (KRAS) is the most frequently altered gene, followed by BRAF, and EGFR41." (PMID 36276638, 2022). "Intriguingly, important tumor-related signatures, such as “G2M checkpoint”, “EMT”, and “apoptosis” were commonly enriched in four different datasets, indicating the important roles of KRAS in cancers." (PMID 35563733, 2022). "Autophagy is elevated in KRAS-driven cancers but not normal tissue and is essential for tumor growth." (PMID 35785187, 2022). "Interestingly, MKNK2a and MKNK2b showed opposite effects on KRAS-G12V-induced colony formation of NCM460 cells, indicating their distinct roles in modulating tumor development." (PMID 33602301, 2021). "Based on the preclinical studies, MEK inhibitors could improved T cell activation, conditioned the tumor microenvironment to facilitate improved response to anti-CTLA-4 treatment and prolonged survival in KRAS-mutant mice in combination with CTLA-4 blockade." (PMID 33402199, 2021). "In one model (BoC71) with four SR tumors, we found two acquired KRAS mutations (G12V & G12C in BoC71 C3 & C4, respectively) and one MAP2K2 (Q60P) mutation (BoC71C1), while the fourth tumor (BoC71 C6) did not reveal any alterations known to drive SR." (PMID 34271981, 2021). "CRC is one of the most frequent cancers, and in particular for KRAS mutant CRC no targeted therapies are available that can successfully treat this type of tumor." (PMID 33691728, 2021). "What takes our study apart is the use of discriminatory multi-target KRAS ddPCR assays to directly identify KRAS SNVs without performing previous tumor NGS." (PMID 33430810, 2021). "The inhibition of the HBP gene (Gfpt1) or non-oxidative PPP genes (Rpia or Rpe) suppresses the KRAS dependent tumor growth." (PMID 33777798, 2021). "A phase 1b dose-escalation, basket expansion study of VS-6766 as a single agent showed promising anti-tumor activity in KRAS non-p.G12C mutant patients with solid tumors (including NSCLC) and multiple myeloma." (PMID 34944952, 2021). "There were similar mutational landscapes in MMRd tumours regardless of aetiology, although co-occurring mutations in PTEN, PIK3CA and KRAS were more common in sporadic MMRd and perturbations of TGF-β signalling more common in LS-EC." (PMID 34572765, 2021). "In addition to prognostic significance, it is increasingly clear that KRAS wild-type PDAC tumours harbour a distinct clinical and genetic profile when compared to KRAS mutant tumours." (PMID 34956889, 2021). "Having established the phenotypic changes in the HMOsisEC10 KRAS and HMOsisEC10 PIK3CA mutant epithelial cell lines, we next examined whether these cells showed altered tumor growth in nude mice." (PMID 34202354, 2021). "It has been shown that in KRAS-dependent tumors, inactivation of WT1 will reduce tumor formation." (PMID 34615983, 2021).
tumor (continued). "This notion is further supported by recent CRISPR/Cas9-mediated gene editing studies revealing that knock-outs of SIK1 and SIK3, but not of other AMPK family members, increased tumor growth in a mouse model of oncogenic KRAS-driven lung adenocarcinoma." (PMID 34142658, 2021). "In summary, these data indicate that the verteporfin treatment inhibits tumor growth and induces apoptosis of KRAS-mutant tumors in vivo without severe side effects." (PMID 33830081, 2021). "In mutant KRAS-driven murine models of NSCLC, genetic deletion of PTPN11 suppressed tumor development, while the dual inhibition of SHP2 and MEK resulted in sustained tumor growth control in murine- and human patient-derived organoids and xenograft models of NSCLC." (PMID 34885068, 2021). "In this context, KRAS-G12D can be released within exosomes by ferroptotic cancer cells and taken up by macrophages through an AGER-dependent mechanism, resulting in the polarization of macrophages to an M2 phenotype and promotion of tumor growth." (PMID 34796174, 2021). "In addition to Wnt activation, CRIS-C tumours exhibit elevated EGFR/ERBB signalling and MYC copy number gains, but typically retain wild-type KRAS, which predicts a good response to EGFR-targeted therapies." (PMID 33673710, 2021). "Furthermore, while PLEXIND1 potentially engages SMAD3 and NRP1 to mediate tumor growth in BxPC-3 cells, the involvement of RAC-1 and KRAS is unclear." (PMID 34439202, 2021). "Then, the RNA expression of genes from the EGFR signaling axis (KRAS, NRAS, BRAF, EGFR, and MET), a tumor stem cell marker (PROM1), EGFR-resistance genes (TRAP1, AXL, PRSS1, and EPHA2) and EGFR-sensitive genes (ERBB3, ERBB2, EREG, AREG, NT5E, and PTEN) were mapped across the pseudotime trajectory." (PMID 34745987, 2021). "Direct KRAS G12V inhibitors are still in the preclinical setting, but they showed promising results in patient-derived xenograft models of NSCLC, CRC and pancreatic cancers, obtaining even complete tumor regressions." (PMID 35004317, 2021). "This is a novel trial in evaluating the clinical benefits of continuing EGFR inhibition versus VEGF inhibition in treating wild-type KRAS, NRAS and BRAF V600E mCRC tumors with second-line cetuximab or bevacizumab plus chemotherapy crossover after tumor progression to first-line cetuximab regimen." (PMID 34335943, 2021). "More importantly, the inhibitory effects of cetuximab on tumor growth were attenuated when SW48 cells were co-injected with KRAS-Mφ or siMOCK-Mφ, but not Ut-Mφ or siKRAS-Mφ." (PMID 33833221, 2021). "The success of this methodology relies largely on the biological selection of transformed cells that express mutant KRAS in the absence of one or both tumor suppressors." (PMID 34491463, 2021). "In line with this prediction, immunohistochemical (IHC) analysis revealed higher levels of p-ERK in KRAS G12D eIF2αS/S than eIF2αA/A lung tumors regardless of the histological tumor type." (PMID 34330898, 2021). "We found that decreased expression of USP12 was present in tumours with different driver gene mutations, suggesting that the downregulation of USP12 is not a phenomenon specifically linked to the KRAS mutant." (PMID 34381028, 2021). "PTC596 is also capable of decreasing tumor growth of human mutant-KRAS xenograft models, encouraging the development of PTC596-based therapies for NSCLC patients carrying KRAS mutations for which no pharmacological indication is available." (PMID 33854168, 2021). "The clinical characteristics including age, gender, tumor location, tumor size, tumor differentiation, AJCC disease stage, KRAS/NRAS/BRAF mutation status, non-quantitative FOBT, serum CEA and CA19-9 were matched between oCRC group and yCRC group." (PMID 34799562, 2021).